INS (insulin)
Diseases named in the same sentence as INS in open-access papers (continued):
Sharing a sentence is not in itself a finding about the gene and the disease.
Impaired glucose tolerance (continued). "In addition, AM2−/− mice exhibit pregnancy induced elevations in blood pressure, serum sFLT-1 levels and AT11 sensitivity along with impaired glucose tolerance associated with elevated levels of insulin and triglycerides in serum." (PMID 36875025, 2023). "In addition, acute exposure to IH in healthy volunteers was associated with decreased insulin sensitivity and impaired glucose tolerance." (PMID 35257355, 2023). "Similarly, elevated fasting blood glucose levels and impaired glucose tolerance during the oral glucose tolerance test have been linked to an increased likelihood of insulin therapy." (PMID 38002781, 2023). "Additionally, it has been suggested that impaired glucose tolerance and upper insulin levels can be the risk factors for gallstones." (PMID 36561321, 2022). "Recent animal studies have suggested that TMAO plays a role in glucose and lipid homeostasis, which may cause impaired glucose tolerance, insulin resistance, oxidative stress in adipose tissue." (PMID 35982495, 2022). "Furthermore, the impaired glucose tolerance observed in HFD‐SHAM was partially caused by diminished capacity of the β cell to secrete insulin even though β cell area was increased as evidenced by HOMA‐β." (PMID 36217558, 2022). "FXR deficient mice exhibited impaired glucose tolerance and reduced insulin sensitivity." (PMID 35321330, 2022). "The subsequent loss of the second phase of insulin secretion could lead to impaired glucose tolerance, and finally to overt T2DM." (PMID 35794584, 2022). "The decrease in β cell mass was associated with impaired glucose tolerance and insulin secretion." (PMID 36107617, 2022). "Concurrently targeting IRS-1 and Lunapark, a nutritionally programmed increase in miR-126-3p causes adipose tissue insulin resistance and an ER stress response, both of which may contribute to impaired glucose tolerance." (PMID 33501603, 2021). "Thus, that gene mutation leads to the loss-of-function defect in insulin production, eventually resulting in impaired glucose tolerance." (PMID 34692549, 2021). "In addition, impaired glucose tolerance and decreased insulin sensitivity is associated with higher plasma insulin levels and altered hepatic glucose metabolism in CD39−/− mice." (PMID 33613285, 2020). "SPARC-deficient mice have been shown to exhibit impaired glucose tolerance and insulin secretion, but the underlying mechanism remains unknown." (PMID 33067534, 2020). "Our findings provide new insight into dopamine-mediated regulation of insulin secretion in primary rat islets, which also explains the cause of impaired insulin secretion and impaired glucose tolerance in Parkinson's disease patients treated with long-term dopaminergic drugs." (PMID 32318020, 2020). "Desynchronization of the circadian system has been linked to several cardiometabolic disorders, including impaired glucose tolerance, reduced sensitivity to insulin, increased markers of systemic inflammation, increased blood pressure, decreased energy expenditure, and increased weight." (PMID 32219098, 2020). "TrkB.T1 KO mice showed impaired glucose tolerance, associated with blunted insulin secretion." (PMID 32327658, 2020). "Women generally have lowered insulin sensitivity (as was also observed in this present study) or increased impaired glucose tolerance than do males, which may increase their susceptibility or sensitivity to dietary influences." (PMID 33537338, 2020). "In our recently published study, we had reported that the chronic alcohol administration associated impaired glucose tolerance was because of the alcohol-induced increase in the ghrelin hormone, which impaired insulin secretion from the islets to decrease serum insulin levels." (PMID 31546643, 2019).
Impaired glucose tolerance (continued). "While CerS2 knockout animals fed a high fat diet, similar to the western diet, display reductions in the C24 series, upregulation of C16:0-ceramide and subsequent impaired glucose tolerance accompanied by high insulin concentration and loss of insulin sensitivity." (PMID 31067249, 2019). "However, with increasing age, insulin secretion in relation to insulin sensitivity decreases in black women and is associated with impaired glucose tolerance and T2D." (PMID 29669711, 2018). "Adaptive immune cells have been reported to be increased in obese mice and humans, which can trigger a sequence of proinflammatory reactions and could be associated with impaired glucose tolerance and insulin sensitivity." (PMID 29415651, 2018). "We also reported that POMC neuron deficiency of Src homology-2 tyrosine phosphatase (Shp2), a major intracellular signaling pathway for leptin, was associated with impaired glucose tolerance and marked attenuation of leptin’s effects to lower plasma glucose and insulin." (PMID 29190687, 2017). "Impaired glucose tolerance of offspring could be caused by reduced sensitivity to insulin that maintains normal blood glucose homeostasis." (PMID 27814245, 2017). "Similarly, prenatal famine exposure was associated with impaired glucose tolerance and insulin secretion in adulthood." (PMID 28451583, 2017). "Impaired glucose tolerance is associated with both impaired early and late phase insulin secretion." (PMID 26840904, 2016). "Frequent excessive postprandial glucose and insulin excursions represent a risk factor for developing diabetes, associated with impaired glucose tolerance (IGT) and impaired insulin tolerance (IIT), inflammation, dyslipidemia, β-cell dysfunction, and endothelial dysfunction." (PMID 28025651, 2016). "To test whether the impaired glucose tolerance in AHR KO mice is caused by reduced insulin release we assessed the insulin secretory capacity of the animals." (PMID 26664351, 2015). "A previous study determined that the mechanisms underlying K and insulin uptake are linked; therefore, hypokalemia may induce impaired glucose tolerance." (PMID 26367380, 2015). "Individuals with an impaired glucose tolerance may initially have high insulin levels, and be at an increased risk for T2D." (PMID 22828963, 2013). "Furthermore, these two phenomena - elevated fasting insulin and reduced acute insulin secretion - are independent predictors of progression from normal to impaired glucose tolerance, which is a known risk factor for development of T2DM." (PMID 23110768, 2012). "Since higher doses of CsA are associated with impaired glucose tolerance, decreased insulin content, and a decreased β-cell volume, we speculated that combining localized CsA microparticles with other immunomodulatory delivery modalities (i.e., CTLA4-Ig) would potentiate allograft protection." (PMID 37765170, 2023). "Likewise, adverse pregnancy outcomes and gestational diabetes in PCOS patients could be linked to preconceptional impaired insulin sensitivity or impaired glucose tolerance." (PMID 33374430, 2020). "Furthermore, a recent study of a non-obese diabetic mouse model showed that the offspring of obese mice, compared with those of non-obese mice, had a significantly increased risk of insulitis and inflammation in the pancreas, impaired glucose tolerance and lower serum insulin." (PMID 29098322, 2018). "Therefore, to evaluate whether one of these tissues contributes to the impaired glucose tolerance in Ripk3-deficient mice, we measured serum insulin levels and performed insulin tolerance tests (ITTs) in WT and KO mice fed with NCD or CD-HFD." (PMID 27323669, 2016). "OGTT revealed impaired glucose tolerance, and ELISA demonstrated reduced serum insulin levels in Card9−/− mice." (PMID 41243316, 2026). "Another study showed that dietary TMAO exacerbated impaired glucose tolerance in high-fat diet-fed mice, increasing fasting insulin levels and HOMA-IR." (PMID 40792244, 2025).
Impaired glucose tolerance (continued). "Knockdown of PFKFB3 or pharmacological inhibition of glycolysis resulted in decreased insulin secretion and impaired glucose tolerance." (PMID 40600018, 2025). "Progressive reduced insulin sensitivity and impaired glucose tolerance were observed in AR knockout mice with advancing age." (PMID 40274775, 2025). "As a key regulator of IR, prolonged injection of 5-HT can lead to impaired glucose tolerance and IR, indicating that changes in serotonin levels can directly affect the body’s ability to effectively use insulin, leading to IR." (PMID 40177494, 2025). "Under normal dietary conditions, osteocalcin-knockout mice exhibit reduced insulin secretion, impaired glucose tolerance, and decreased insulin sensitivity." (PMID 41356002, 2025). "Aerobic exercise enhances insulin sensitivity to lower blood glucose levels, whereas resistance exercise increases muscle mass, thereby improving impaired glucose tolerance and glycogen storage capacity." (PMID 41090267, 2025). "Although male F1 offspring develop impaired glucose tolerance and insulin secretion in adulthood, female F1 offspring appear protected until pregnancy unmasks a loss of glucose control." (PMID 40859436, 2025). "As individuals progress from normal glucose tolerance to impaired glucose tolerance, insulin sensitivity decreases markedly, while the decline in glucose tolerance remains relatively modest due to a compensatory rise in insulin secretion." (PMID 40004800, 2025). "(2013) showed dramatic metabolic dysfunction in the LRT model, as evidenced by impaired glucose tolerance, whole‐body insulin sensitivity, and elevated circulating insulin concentration." (PMID 40720691, 2025). "In the present study, we found that after 12 weeks of HFD, mice displayed high levels of fasting blood glucose and serum insulin, which led to impaired glucose tolerance and insulin tolerance." (PMID 41002956, 2025). "Nevertheless, this regimen impaired glucose tolerance in women, attributed to decreased insulin sensitivity." (PMID 41439931, 2025). "As individuals progress from normal glucose tolerance to impaired glucose tolerance, insulin sensitivity declines significantly, while the deterioration of glucose tolerance remains relatively mild due to a compensatory increase in insulin secretion." (PMID 40004800, 2025). "The loss of β-cells is not the only factor that causes complications; IL-1β production also plays a critical role in chronic inflammation in T2D as it interferes with insulin signaling, resulting in impaired glucose tolerance and reduced insulin sensitivity." (PMID 40216765, 2025). "GDM, like T2DM, is characterized by reduced insulin sensitivity, impaired glucose tolerance, and dyslipidemia." (PMID 39984726, 2025). "Elevated GH concentrations directly attenuate insulin signalling and stimulate lipolysis, decreasing glucose uptake in peripheral tissues, thus leading to the development of impaired glucose tolerance and DM." (PMID 39859181, 2025). "c, We demonstrated temporal alignment of β-cell defects with systemic phenotypes with a clear sequence of events: β-cell dysfunction emerged first (6–7 weeks of age), characterized by impaired glucose tolerance and reduced insulin secretion." (PMID 41234234, 2025). "EBE also ameliorated impaired glucose tolerance and insulin sensitivity, liver inflammation, steatosis, fibrosis, and dysfunction in high-AGE-fed rats." (PMID 41470863, 2025). "The fasting blood glucose level was elevated, and the symptoms of impaired glucose tolerance and insulin sensitivity were observed, along with an increased glycated hemoglobin (HbA1c) percentage and a decreased serum insulin level." (PMID 40225857, 2025). "Excessive selenium intake (0.8 mg Se/kg) significantly disrupted glucose homeostasis, as evidenced by elevated fasting blood glucose levels, increased insulin secretion, impaired glucose tolerance, and reduced insulin sensitivity." (PMID 39861441, 2025).
Impaired glucose tolerance (continued). "Functionally, impaired glucose tolerance (IGT), a key prediabetic state, is associated with reduced first- and second-phase insulin secretion and lower total insulin content normalised to beta cell mass." (PMID 40768044, 2025). "The results indicate that NDPKB−/− mice exhibit pre-diabetic characteristics such as impaired glucose tolerance with normal insulin secretion, and normal insulin sensitivity." (PMID 39985023, 2025). "In human trials, chlorogenic acid has been shown to reduce postprandial glucose and insulin responses during oral glucose tolerance tests, as well as improving fasting glucose levels and insulin sensitivity in individuals with impaired glucose tolerance." (PMID 40332518, 2025). "Plasma glucose levels and insulin concentrations in individuals with normal glucose tolerance and impaired glucose tolerance show a positive correlation during an oral glucose tolerance test." (PMID 41009753, 2025). "Impaired glucose tolerance and reduced glucose-induced insulin secretion were appeared in β-cell-specific PIEZO1 knockout mice because of decreased β-cell electrical activity and Ca2+ elevation." (PMID 39781454, 2025). "The liver-specific deletion of BVRA increased fasting glucose and insulin levels, potentially due to reduced hepatic insulin signaling and impaired glucose tolerance." (PMID 41300483, 2025). "The diabetic control-group rats exhibited impaired glucose tolerance due to the marked reduction in serum insulin levels, compromised β-cell function, and substantial rise in lipid profile and oxidative stress parameters." (PMID 41227734, 2025). "HUA-fed mice exhibited a dynamic increasing fasting glucose, impaired glucose tolerance, and decreased peripheral insulin sensitivity compared with SCD-fed controls." (PMID 40710003, 2025). "Consistent with earlier research, our findings showed that HFD led to impaired glucose tolerance and reduced insulin sensitivity (respectively)." (PMID 39747658, 2025). "Pregnant Restricted females were previously shown to have impaired glucose tolerance, demonstrated through reduced insulin AUC and increased glucose AUC in response to IPGTT." (PMID 40859436, 2025). "Aging is a strong risk indicator for cancer; the aging process itself is accompanied by metabolic decline, such as reduced insulin sensitivity and impaired glucose tolerance, both of which directly influence eGDR levels." (PMID 41310487, 2025). "Coupled with impaired glucose tolerance, the reduction in blood glucose in response to the insulin challenge in the insulin tolerance test (ITT) was also significantly reduced in mice with COVID‐19 vaccination (week 4) (p < 0.05, in all cases)." (PMID 41190280, 2025). "Under chow diet feeding, mutant mice had reduced fasting insulin levels and impaired glucose tolerance." (PMID 41052246, 2025). "Dietary TMAO supplementation exacerbates impaired glucose tolerance in high-fat diet-fed mice by disrupting hepatic insulin signaling and inducing adipose tissue inflammation, thereby elevating HOMA-IR indices." (PMID 40395816, 2025). "In these circumstances the cells are unable to take up more glucose (impaired glucose tolerance or prediabetes), either because of a failure of insulin secretion or decreased insulin sensitivity." (PMID 39859540, 2025). "Similar patterns of reduced insulin sensitivity and impaired glucose tolerance are also seen during non‐obese mouse and human pregnancy." (PMID 40023799, 2025). "Studies have shown that individuals with acne, especially adult males, exhibit higher fasting insulin levels and impaired glucose tolerance compared to controls." (PMID 40358870, 2025). "The low levels of gonadotropins, especially FSH, also impaired glucose tolerance due to insufficient insulin secretion." (PMID 41237113, 2025).
Impaired glucose tolerance (continued). "In line with the glucose metabolism dysfunction caused by HOP, Dityr supplementation produced comparable effects, including elevated fasting blood glucose, impaired glucose tolerance, and reduced insulin secretion." (PMID 41008194, 2025). "The T2DM model was successfully established, as evidenced by increased body weight, food intake, water consumption, and impaired glucose tolerance and insulin tolerance." (PMID 39996573, 2025). "Animal models have shown that nutrient-derived TMAO can exacerbate impaired glucose tolerance and increase fasting insulin levels by blocking the hepatic insulin signaling pathway and causing inflammation in adipose tissue." (PMID 39997751, 2025). "This neuroprotection was accompanied by reduced fasting glucose and insulin levels, impaired glucose tolerance, free fatty acids and corticosterone." (PMID 39759452, 2024). "FGR diminishes the β-cell mass responsible for insulin secretion and increases peripheral glucose and insulin sensitivity, which leads to impaired glucose tolerance and the onset of T2DM later in life." (PMID 38951934, 2024). "The DDC-fed mice showed increased body weight, impaired glucose tolerance, and insulin sensitivity, as well as increased lipid profiles compared to the mice fed a standard chow diet (CD)." (PMID 39462409, 2024). "In humans with impaired glucose tolerance, added chromium improved insulin efficiency and thus serum glucose levels." (PMID 39487755, 2024). "Pancreatic β-cells secrete insulin in a biphasic manner, first- and second-phase insulin secretion, and first-phase insulin release is almost lost in patients with impaired glucose tolerance or in the early stages of T2D8." (PMID 38514666, 2024). "Intriguingly, while male mice exhibited only impaired glucose tolerance, female mice also demonstrated increased weight and elevated serum insulin levels, among other symptoms." (PMID 38251002, 2024). "RL-exposed mice exhibited worsened metabolic profiles, including impaired glucose tolerance/insulin sensitivity, elevated lipid levels, and reduced serum insulin levels." (PMID 39770951, 2024). "It is known, that HDBR conditions affect carbohydrate metabolism - insulin secretion increases and impaired glucose tolerance develops." (PMID 38966226, 2024). "Consistent with prior studies, GDM-E18.5 mice displayed impaired glucose tolerance and reduced insulin sensitivity compared to ND-E18.5 mice." (PMID 39599611, 2024). "We found that mice in the OB group had higher levels of FBG and HbA1c, accompanied by impaired glucose tolerance and insulin sensitivity as well." (PMID 39156823, 2024). "In our study, although KD2 lowered fasting blood glucose levels, it still led to impaired glucose tolerance, accompanied by a decrease in insulin secretion." (PMID 39398341, 2024). "In this study, diabetic animals showed significant increase in blood glucose level, with a marked decline in serum insulin levels and impaired glucose tolerance." (PMID 39070783, 2024). "We confirmed that Stat5 plays a key role in the regulation of insulin secretion by B7-H4 and that inhibiting Stat5 can reverse impaired glucose tolerance and insulin secretion in B7-H4 cKO mice." (PMID 39571901, 2024). "Patients with impaired glucose tolerance showed an enhanced nutrition-related succinate response, which correlates with the potentiation of insulin secretion during intravenous glucose administration." (PMID 38713514, 2024). "Along with the diminished insulin secretory response to direct (intravenous) glucose loading in the case of β-cell dysfunction during impaired glucose tolerance, the IdIR is also decreased." (PMID 38966210, 2024). "HC diet impaired glucose tolerance manifested by a significantly lower area under the curve (AUC), as well as reduced glucose and increased insulin." (PMID 39300527, 2024).